IL22 (interleukin 22)
Diseases named in the same sentence as IL22 in open-access papers (continued):
Sharing a sentence is not in itself a finding about the gene and the disease.
psoriasis (continued). "The topical application of Aldara in mice deficient in IL-17A, IL-17F, or IL-22 drastically reduced the severity of psoriasis." (PMID 29249871, 2017). "Tissue resident Th22 together with CD8 Tc17 cells have been proposed as repository of disease memory in sites of recurrent psoriasis and because of the action of IL-22 on keratinocytes, they are linked to the most prominent histological features of psoriasis." (PMID 27595115, 2016). "Psoriasis is associated with activation of an IL-22 and IL-6/STAT3 pathway, which contributes to keratinocyte hyperproliferation and failure to exit the cell cycle with the inability to fully mature into corneocytes." (PMID 27537526, 2016). "In mouse imiquimod models of psoriasis, IL-22-deficient mice have an evident decrease in the formation of psoriasis-like lesions, in particular pustule formation and acanthosis." (PMID 27595115, 2016). "In animal models, IL-22 blockade or IL-22 deficiency is associated with a less severe form of experimental psoriasis." (PMID 27148267, 2016). "Recent evidence indicates that IL-22 is an important cytokine for the protection and tissue remodelling of the skin, whereas Tc22 cells have been implicated in the pathogeneses of psoriasis and atopic dermatitis." (PMID 27286889, 2016). "Together with other cytokines, such as TNFα, IL-17, and IL-20, IL-22 therefore takes part in the formation of the cytokine network that orchestrates the progression of the different pathogenic features of psoriasis." (PMID 27595115, 2016). "Psoriasis is another disease in which IL-22 is clearly pathogenic and is a key mediator in its late stage, leading to keratinocyte lesions." (PMID 27148267, 2016). "IL-22-deficient mice, or mice treated with IL-22 neutralizing antibodies were protected against psoriasis induced by imiquimod." (PMID 26416167, 2015). "In human skin cultures, chemerin is significantly downregulated by IL-17 and IL-22, key cytokines implicated in psoriasis, whereas it is upregulated by acute phase cytokines oncostatin M and IL-1β." (PMID 25659101, 2015). "Interleukin-22 (IL-22), a Th17-linked cytokine, is associated with autoimmune diseases such as inflammatory bowel diseases and psoriasis." (PMID 26077779, 2015). "The clinical efficacy of anti-TNF-α drugs in patients with psoriasis and/or joint disease was associated with (i) reduction of IL-6 and IL-22 in sera; (ii) increments of regulatory T cells; (iii) reduction of cutaneous homing receptor expressing T cells." (PMID 25136144, 2014). "IL-22 is pathogenic in psoriasis and protective in inflammatory bowel disease, hepatitis, Klebsiella pneumonia, myocarditis, ulcerative colitis, airway inflammation and autoimmune allergic asthma." (PMID 24676270, 2014). "In a three-dimensional human epidermis model, IL-22 and IL-20 cause psoriasis-like morphologic changes associated with the inhibition of keratinocyte terminal differentiation and STAT3 upregulation." (PMID 23365685, 2013). "It is generally believed that psoriasis is a T cell-mediated autoimmune disease in which the IL-23/Th17 pathway and the Th17-associated cytokines, IL-17 and IL-22, are considered to be involved." (PMID 22808266, 2012). "The IL-10 cytokine shows the opposite effect to IL-22, as the SNP observed in the vicinity of the IL-10 gene shows a clear genomic association with psoriasis." (PMID 21152006, 2010). "IL-22, IL-20, IL-26 and IL-18 have all been implicated in inflammatory conditions such as Crohn's disease and Psoriasis in humans." (PMID 20950493, 2010). "The description of the homeostatic mechanism from the systems perspective explains why SNPs in some cytokines (e.g. in IL-22), can have very low statistical association with psoriasis, but can contribute to pathology in a number of cases." (PMID 21152006, 2010).
psoriasis (continued). "In psoriasis, skin lesions arise from complex processes involving maladaptive immune signalling among keratinocytes, dendritic cells, neutrophils and T-cells; implicated pathways include IL-17A, IL-22, IL-23 and TNF-α signalling." (PMID 39959848, 2025). "Moreover, other psoriasis-related pathogenic cytokines like IL22 and TNF-α were downregulated in αβT from Lztr1-deficient mice." (PMID 41162356, 2025). "The high amounts of circulating inflammatory biomarkers, such as CRP and IL-22, which were streamed from skin lesions into the bloodstream, may serve to explain the association between the severity of psoriasis and respiratory disorders." (PMID 40005314, 2025). "In IL-22-associated diseases, including psoriasis and atopic dermatitis, IL-22 may induce conjunctivitis." (PMID 40861543, 2025). "Notably, the release of inflammatory factors, such as tumor necrosis factor (TNF-α), interferon (IFN)-γ, interleukin (IL)-17, IL-22, IL-23, and IL-1β, is the primary cause of psoriasis." (PMID 39684717, 2024). "Furthermore, KCs stimulated by a combination of psoriasis-associated cytokines (TNF-α, IL-1A, IL-17A, IL-22, and oncostatin M) activate autophagic flux, which leads to recurrent psoriasis inflammation and increased skin barrier damage." (PMID 38606161, 2024). "Furthermore, dysregulation of IL-22 production by Th17 cells has been linked to a variety of inflammatory skin diseases, including psoriasis, atopic dermatitis (AD), and allergic contact dermatitis (ACD)." (PMID 38879568, 2024). "IL-17 and IL-22 are cooperatively associated with psoriasis pathogenesis." (PMID 38348035, 2024). "Moreover, we identified an association between Streptococcus abundance and psoriasis severity in patients with genetic variants related to IL-22, ERAP1, NOS2, and ILF3." (PMID 38898675, 2024). "Both pro-inflammatory cytokine family members are of paramount importance in the pathogenesis of psoriasis, exhibiting a diverse role through the recruitment of neutrophils and the causal interplay with keratinocytes considering the IL-17 family, while IL-22 promotes the keratinocyte proliferation." (PMID 37108251, 2023). "The expression of many genes known to be associated with psoriasis, including Lce3f, Sprr2b, Krt15, S100a8, S100a9, Il17a, Il17f, Il18, Il20, Il22, and Ccl20, was downregulated in the skin of IMQ-treated Camk4−/− mice compared with those of IMQ-treated Camk4+/+ mice." (PMID 35869084, 2022). "However, IL‐22‐expressing T cells have been implicated in the pathogenesis of psoriasis and research has shown the role of lipid‐specific T‐cells responses to be an important factor in skin inflammatory conditions." (PMID 34913478, 2022). "Most studies that focus on immune diseases, such as rheumatoid arthritis, psoriasis or multiple sclerosis, and the key factors related to pathogenic differentiation of Th17 and Th22 cells and the production of IL-17 and IL-22 in their course, emphasize the pro-inflammatory importance of IL-6." (PMID 35407663, 2022). "A missense single‐nucleotide polymorphism (rs33980500; SNP‐D10N) in the coding region of ACT1 was suggested to increase the compensatory Th17 cells, with excessive secretion of IL‐22 and IL‐17 being the main cause of psoriasis susceptibility in ACT1‐D10N patients." (PMID 34936223, 2022). "IL-22 has been implicated in both psoriasis and several lung diseases." (PMID 35163689, 2022). "Pollock proposed IL-22 as a possible germ line risk locus for PsA Furthermore, Nikamo found that a high-risk IL-22 promoter variant might lead to the onset of psoriasis before puberty." (PMID 35911703, 2022). "However, it was also reported that IL-22 is linked to inflammatory tissue pathology and plays roles in the pathogenesis of autoimmune diseases like psoriasis." (PMID 34944732, 2021). "We examined whether the key cytokines (TNFα, IL-22, IL-1β, IL-17A) implicated in the pathogenesis of psoriasis modulate the circadian oscillation of the clock genes in HaCaT keratinocytes." (PMID 35008548, 2021).
psoriasis (continued). "The notable exception is psoriasis and other dermatitides where IL-22 has a pathogenic effect, which likely involves direct actions of IL-22 on keratinocytes leading to excessive proliferation, aberrant maturation as well as induction of inflammatory mediators." (PMID 33692792, 2021). "This is consistent with the well documented pathogenic role of IL-22 in rodent models of psoriasis." (PMID 33692792, 2021). "Additionally, future models should investigate other cytokines that are implicated in psoriasis, such as IL-22." (PMID 33500449, 2021). "The links between synovitis and CP are further established by the fact that an IL-22 associated mechanism increased synovial inflammation in RA joints and clinical attachment loss in CP patients, mimicking IL-22 pro-inflammatory function in psoriasis." (PMID 34776994, 2021). "Moreover, IL-22 has a pathogenic role in psoriasis, and IFN-γ can enhance the basic expression of a-STAT3, thereby weakening the response of keratinocytes to IL-22." (PMID 34044769, 2021). "At the same time, the effect of dsRNA on TLR3 is a proven trigger of apoptosis and necroptosis and upregulation of IL-17 and IL-22 in the psoriasis model is associated with a decrease in the expression of a RIPK-1, traditionally considered as a necroptosis component." (PMID 33240882, 2020). "However, constitutive or chronic overexpression of IL-22 can have pathogenic properties, for instance in some liver disorders, psoriasis, rheumatoid arthritis and cancers, which require special attention 50-51." (PMID 32483425, 2020). "STAT3 participates in signaling downstream of multiple cytokines implicated in psoriasis, such as IL-6, IL-10, IL-20, IL-22, and IL-23, and may have a role in mediating the innate immune response in psoriatic epidermis." (PMID 32752186, 2020). "Notably, others have found that the rs2227483 genotype TT is statistically associated with early-onset psoriasis through the high production of IL-22 cytokine." (PMID 32148440, 2020). "Indeed, IL-22 inhibits keratinocyte terminal differentiation and induces psoriasis pathogenic signature in keratinocytes." (PMID 32345660, 2020). "However, IL-22 is pathogenic in some inflammatory settings, such as psoriasis, allergic airway inflammation, and collagen-induced arthritis." (PMID 32843067, 2020). "In the DEX group, the expressions of IL-1β, IL-6, TNF-α, IL-17, and IL-22 were significantly lower than the model group (p < 0.05), suggesting that the expressions of inflammatory cytokines associated with psoriasis have been inhibited after the intervention of DEX." (PMID 32090080, 2020). "Furthermore, normal human keratinocytes show increased expression of IL-1 group mRNA after treatment with psoriasis-associated cytokines (TNFα, IL-1α, IL-17,IL-22)." (PMID 32484435, 2020). "In psoriasis patients, the expression of this natural inhibitor is downregulated in non-lesional skin, and such downregulation is associated with an increased sensitivity of the skin to the pathogenetic action of IL-22." (PMID 31028434, 2019). "Independently from IL-17, IL-22 was also demonstrated to increase synovial inflammation in rheumatoid arthritis joints and clinical attachment loss in periodontitis patients, similarly to its proinflammatory function in psoriasis." (PMID 31295952, 2019). "Current research showed that the accumulation and activation of ILC3 cells in experimental autoimmune encephalomyelitis (EAE), circulating ILC3s, as a major source of IL-17/IL-22, have recently been identified as associating with psoriasis and psoriatic arthritis." (PMID 31454926, 2019). "However, overall psoriasis-associated genes and genes belonging to signaling pathways of IL-22, IFNγ, TNFα, IL-1, and IL-17 were more strongly suppressed by ustekinumab than by etanercept." (PMID 31673756, 2019).
psoriasis (continued). "In addition, atopic dermatitis, which exhibits a dominant Th2 response, is associated with lower levels of IL-22 expressions as compared to psoriasis characterized by enhanced Th1/Th17 responses." (PMID 29075900, 2018). "One of the nice examples may be psoriasis, in which the pathogenic potential of IL-22 is elicited only in the presence of IL-17 and IFN-γ." (PMID 29075900, 2018). "Additionally, elevated IL-22-producing Th17 cells are associated with disease activity in various inflammatory diseases, such as psoriasis, asthma, and multiple sclerosis (MS)." (PMID 28030850, 2017). "Additionally, psoriasin is a chemotactic for CD4+ T cells and neutrophils, and is induced by psoriasis-associated inflammatory cytokines that include IL-1β, IL-17, IL-22, and TNF-α." (PMID 28360856, 2017). "The role of IL-22 in psoriasis pathogenesis has been linked to keratinocyte activation and to the formation of epidermal acanthosis, a prominent morphologic feature of psoriasis." (PMID 27595115, 2016). "Thus, neonatal elimination of gut microbiota increases the susceptibility to imiquimod-induced psoriasis in adults, which is likely attributed to the increase in IL-22-producing T cells, especially γδ+ T cells." (PMID 26416167, 2015). "A further example of pathogenic IL-22 functions is psoriasis." (PMID 23382730, 2013). "In addition, IL-17A plays an important role in cutaneous defense by the cooperation with other psoriasis-associated cytokines such as IL-22, TNF-α and IL-1 which have been implicated in a synergistic induction of AMP in keratinocytes." (PMID 23555696, 2013). "As was the case with IL-17Apos CD8 T cells, also the percentage of IL-22pos CD8 T cells was much higher in the epidermis than in the adjacent dermis of psoriatic skin, but not in normal skin, underlining a possible role of IL-17A and IL-22 producing CD8 T cells in the pathogenesis of psoriasis." (PMID 21124836, 2010). "In addition, KC differentiation can be inhibited by IL-22 via downregulation of differentiation-related genes, resulting in hyperplasia of the KC layers and psoriasis-like epidermal alterations, including acanthosis, loss of granular layer, and a compact cornified layer." (PMID 41467015, 2025). "More severe forms of psoriasis are associated with a high degree of inflammation, that are confirmed by psoriatic skin lesions and numerous inflammatory mediators such as TNFα, IL-1, IL- 6, IL-8, IL-17, IL-22, IL-23, INF-ɣ, homocysteine and hsCRP, which highly correspond with disease activity." (PMID 39858442, 2025). "Additionally, Th22 cells contribute to this process by producing IL-22, and emerging evidence suggests that Th22 cells may be implicated in the recurrence of psoriasis." (PMID 39684717, 2024). "Since a direct link has been demonstrated between inflammatory diseases of the skin, associated with chronic inflammation such as psoriasis, with atherosclerosis, and of cardiovascular diseases, we also used a keratinocyte model, in which a psoriatic phenotype has been induced with IL-22 treatment." (PMID 33525692, 2021). "The multiple effects of IL-22 mediate epithelial barrier protection in the steady state but can also induce tissue pathology when dysregulated; hence this cytokine has been implicated in inflammatory disorders of epithelial surfaces including psoriasis and inflammatory bowel disease (IBD)." (PMID 28330898, 2017). "Notably, IL-22 deficiency or blockage ameliorates disease in experimental psoriasis." (PMID 23382730, 2013). "Psoriasis is a chronic skin disease characterized by keratinocyte hyperproliferation and inflammation, largely driven by the cytokines IL-22 and interferon (IFN)-γ." (PMID 42103703, 2026). "We found that SHIN1 reduced keratinocyte proliferation, particularly under IL-22 stimulation, and restored differentiation in ex vivo psoriasis skin explants by reversing the effects of IL-22." (PMID 42103703, 2026).
psoriasis (continued). "Since keratinocytes express receptors for this interleukin, IL-22 is involved in the pathogenesis of various skin diseases such as atopic dermatitis or psoriasis, but its role in cutaneous warts has been poorly studied." (PMID 40142865, 2025). "Psoriasis is marked by dysregulated cytokine activity, particularly IL-23, IL-17, and IL-22, that not only intensifies immune activation but also impairs normal KCs differentiation and promotes excessive epidermal growth." (PMID 41226338, 2025). "In psoriasis, Th17 cells produce IL-17A and IL-22, cytokines that lead to keratinocyte proliferation and contribute to the thick, scaly plaques characteristic of the disease​." (PMID 40161116, 2025). "Inflammatory factors in psoriasis patients, such as TNF-α, IL-6, IL-22, etc., in addition to causing skin lesions, also promote the occurrence of metabolic disorders and increase the risk of MetS." (PMID 40385577, 2025). "Elevated IL-22 levels have been linked to the pathogenesis of various inflammatory diseases, including psoriasis and inflammatory bowel disease, with IL-22 blockade showing therapeutic promise." (PMID 41357311, 2025). "Th17 cells, distinguished by their secretion of IL-17 and IL-22, have since been recognized as central players in psoriasis pathogenesis." (PMID 41226338, 2025). "Once activated, these cells produce high levels of IL-17 and IL-22, which promote keratinocyte proliferation and inflammation, driving the inflammatory cascade in psoriasis." (PMID 39800748, 2025). "IL-23 also stimulates T cells to produce IL-17A, IL-17F, and IL-22, which are key effector cytokines in the pathogenesis of psoriasis, activating and proliferating keratinocytes." (PMID 41376622, 2025). "The psoriasis-relevant cytokines IL-17 and IL-22 have been shown to be produced and secreted in vivo by Th17 and Th22 cells." (PMID 40678130, 2025). "Next, to better simulate the inflammatory cascade characteristic of psoriasis, we stimulated KCs with a combination of IL‐22, IL‐17A and TNF‐α, known to synergistically enhance the proinflammatory effects of IL‐22 in KCs." (PMID 40038877, 2025). "Psoriasis is a particularly illustrative example: it is triggered by excessive IL-17/IL-22 signaling and is characterized by hyperproliferation of keratinocytes." (PMID 41009535, 2025). "This activation initiate differentiation of Th22 and Th17 cell subsets, result in generation of a cascade of psoriasis-associated cytokines including interferon-gamma (IFN-γ), TNF-α, IL-22, and IL-17." (PMID 40818978, 2025). "Psoriasis is classified as a T cell-mediated disorder, as T cell-derived cytokines like IL-17A and IL-22 are responsible for the hyperproliferation and abnormal differentiation of keratinocytes, leading to the formation of psoriatic plaques." (PMID 39859462, 2025). "Molecules such as S100A7 (psoriasin) and squamous cell carcinoma antigen 2 (SCCA2), which are induced by IL-17/IL-22 in psoriasis, are also overexpressed in oral SCC and have been shown to promote keratinocyte proliferation and invasion." (PMID 41009535, 2025). "In psoriasis, the prominent Th17 component establishes IL-17 and IL-22 as reliable biomarkers for target engagement." (PMID 41301460, 2025). "This is in agreement with several previous biomarker studies of the PDE4 inhibitor apremilast in psoriasis patients, showing a significant modulation of TH1 and TH17 cytokines involved in the pathogenesis of psoriasis (e.g., IL‐17A/F, IL‐22 and TNFα)." (PMID 40970551, 2025). "IL-22 expression is significantly increased in both psoriatic skin lesions and the serum of individuals with psoriasis when compared to healthy controls." (PMID 40731810, 2025). "Th17 cells produce cytokines such as IL-6, IL-17, and IL-22, which help drive inflammation and rapid skin cell growth seen in psoriasis, leading to the development of plaques." (PMID 40507817, 2025).